ADAMTS15 (ADAM metallopeptidase with thrombospondin type 1 motif 15)
Description:
Metalloprotease which has proteolytic activity against the proteoglycan VCAN, cleaving it at the 'Glu-1428-|-1429-Ala' site. Cleaves VCAN in the pericellular matrix surrounding myoblasts, facilitating myoblast contact and fusion which is required for skeletal muscle development and regeneration.
Synonyms: DA12
Tractability: Antibody: UniProt places it where antibodies can reach, with medium confidence; UniProt predicts a signal peptide or a membrane-spanning region; its Gene Ontology location is reachable by antibodies, with medium confidence.
Gene: Protein-coding gene on chromosome 11 (130,448,645 to 130,476,645, forward strand). Ensembl gene ENSG00000166106.
Subcellular location: Secreted, extracellular space, extracellular matrix; Cell surface
Subcellular location (Human Protein Atlas): Cytosol; Predicted to be secreted
Pathways (Reactome):
Disease: Defective B3GALTL causes PpS
Metabolism of proteins: O-glycosylation of TSR domain-containing proteins
Gene Ontology:
Molecular function: endopeptidase activity; metalloendopeptidase activity; extracellular matrix binding; heparin binding; metallopeptidase activity; zinc ion binding
Biological process: extracellular matrix disassembly; extracellular matrix organization; myoblast fusion; proteolysis
Cellular component: cell surface; extracellular matrix; extracellular region
Genetic constraint (gnomAD): Loss-of-function variants: 29 observed, 65.99 expected, observed/expected ratio (o/e) 0.44, 90% interval 0.33 to 0.6. The upper end of that interval is the gene's LOEUF score, 0.6, which puts it in group 2 of 6, group 1 being the genes least tolerant of losing a copy. Missense variants: 1,251 observed, 1,244.4 expected, observed/expected ratio (o/e) 1.01, 90% interval 0.96 to 1.05. Synonymous variants: 585 observed, 534.94 expected, observed/expected ratio (o/e) 1.09, 90% interval 1.02 to 1.17.
Homologues: Orthologues: chimpanzee ADAMTS15 (99% identical), macaque ADAMTS15 (99% identical), pig ADAMTS15 (93% identical), rabbit ADAMTS15 (93% identical), rat Adamts15 (93% identical), mouse Adamts15 (93% identical), guinea pig ADAMTS15 (89% identical), tropical clawed frog adamts15 (70% identical), dog ADAMTS15 (63% identical), zebrafish adamts15a (63% identical), zebrafish adamts15b (62% identical). Paralogues in human: ADAMTS1 (49% identical), ADAMTS9 (43% identical), ADAMTS8 (43% identical), ADAMTS20 (40% identical), ADAMTS5 (40% identical), ADAMTS4 (39% identical), ADAMTS7 (35% identical), ADAMTS16 (33% identical), ADAMTS6 (33% identical), ADAMTS18 (32% identical), ADAMTS12 (32% identical), ADAMTS2 (31% identical), and 13 more.
Diseases named in the same sentence as ADAMTS15 in open-access papers:
ADAMTS15 is named in the same sentence as 26 diseases in open-access papers, as found by Europe PMC text mining. Sharing a sentence is not in itself a finding about the gene and the disease. The quoted sentences say what the papers report.
breast carcinoma (17 papers, 2012 to 2025). "Low expression of ADAMTS15 was demonstrated to be associated with poor prognosis in breast carcinoma." (PMID 36354023, 2022). "Expression of ADAMTS-15 in breast cancer cells reduced cell migration, which was associated with enhanced cell surface display of Syndecan-4." (PMID 35883515, 2022). "Furthermore, ADAMTS1 has been implicated in promoting atherosclerosis and ADAMTS15 acts as a tumor suppressor in breast carcinoma, potentially through proteoglycan proteolysis." (PMID 29518972, 2018). "In parallel studies for downregulated genes, we were able to identify seven genes with mutations in colon cancer (DPP10, PCSK2, ADAM33, RELN, CAPN13, ADAMTS1 and ADAMTS15), and five genes with mutations in breast carcinomas (MASP3, ABHD12B, TLL1, CPA3 and DPP6)." (PMID 24243807, 2013). "In another study, ADAMTS-15 expression was correlated with improved prognosis in women with breast cancer, reduced motility of breast cancer cell lines, and decreased tubule formation in endothelial cell lines." (PMID 39682243, 2024). "Recent reports suggest that ADAMTS2 is overexpressed by gastric cancer cells, COL14A1 is downregulated in breast cancer cells, and ADAMTS15 functions as a tumor suppressor role in prostate cancer." (PMID 37552338, 2023). "ADAMTS15 is used to predict the survival of human breast carcinoma with the inhibitory functions to tumor growth and invasion of colorectal cancers." (PMID 36164519, 2022). "ADAMTS-15 decreases the migration of MDA-MB-231 and MCF-7 breast cancer cells in association with the increased cell surface expression of SDC4." (PMID 34282767, 2021). "ADAMTS15 inhibits tumor cell migration and angiogenesis in breast cancer and serves as an independent prognostic factor of this cancer type." (PMID 32884571, 2020). "Enforced expression of ADAMTS-15 was able to reduce motility of breast cancer cells and decrease angiogenesis independently of its catalytic activity." (PMID 32354091, 2020). "Among which, ADAMTS15 alone, emerged as a predictor of prolonged event-free survival and was shown to be significantly down-regulated in grade 3 breast carcinomas compared to grades 1 and 2 breast carcinomas." (PMID 24213506, 2012). "ADAMTS15 expression is a favorable prognostic factor in breast cancer." (PMID 38217262, 2024). "ADAMTS15 may be acting as a tumor suppressor in breast cancer by modulating cell‐environment interactions." (PMID 38217262, 2024). "As ADAMTS15 high levels are signs of good prognosis in breast cancer." (PMID 38217262, 2024). "The expression level of ADAMTS-15 is closely related to the prognosis of breast cancer." (PMID 35883515, 2022). "Moreover, silencing of SDC4 expression rescued the effect of ADAMTS-15 on cell motility in breast cancer cells." (PMID 34282767, 2021). "Inhibition of mammary cancer cell migration by ADAMTS-15 requires SDC4." (PMID 34282767, 2021). "Metalloproteases such as ADAMTS15 have been reported to inhibit breast cancer cell migration, and their reduced expression could accelerate breast cancer progression in AA women." (PMID 32824813, 2020). "Moreover, ADAMTS-15 expression positively correlated with improved prognosis in breast cancer patients." (PMID 32354091, 2020). "Moreover, both wild-type and catalytically-inactive (E363A) ADAMTS15 were able to reduce breast cancer cell migration on matrices of fibronectin or laminin." (PMID 29518972, 2018). "ADAMTS15 is a metalloprotease known to inhibit breast cancer cell migration, and it is possible that the reduced expression of this gene could have consequences in AA BRCa progression." (PMID 24324792, 2013). "In addition, they showed that ADAMTS8, along with ADAMTS15, are novel predictors of survival in breast cancer patients." (PMID 24213506, 2012). "Grade-specific down-regulation of ADAMTS15 transcript in breast cancer." (PMID 24213506, 2012).
breast carcinoma (continued). "Other selected genes, SLC40A1, ADAMTS15, THSD4, GREB1, and SLC44A4 have been reported to be related to breast cancer, and ZG16B, FDCSP, and SRARP have been associated with other types of tumors." (PMID 32795265, 2020). "ADAMTS12 enhances tumor cell migration in PDAC, while ADAMTS15 increases cellular motility without affecting proliferation in breast cancer, paralleling the lack of a proliferative effect observed for ADAMTS13 in our study." (PMID 41211185, 2025). "However, thus far, the only documented substrates for ADAMTS-15 are VCAN and aggrecan, while in breast cancer, where the effects of ADAMTS-15 on cell migration were shown to involve syndecan-4, this was independent of its metalloproteinase activity." (PMID 32354091, 2020). "Overexpression of either ADAMTS15 or its catalytic active site mutant did not impact cell proliferation or adhesion in two types of breast cancer cells." (PMID 24213506, 2012). "Enhanced expression of ADAMTS-15 might reduce the motor ability of breast cancer cells and angiogenesis, rather than rely on its catalytic activity." (PMID 36845403, 2023).
prostate carcinoma (7 papers, 2012 to 2024). A carcinoma that arises from epithelial cells of the prostate gland. "Analysis of ‘androgen-responsive’ LNCaP prostate cancer cells in vivo in NOD/SCID mice revealed that ADAMTS-15 expression caused slower growing tumors, which resulted in increased survival." (PMID 32354091, 2020). "ADAMTS15 is found to be one of the genes expressed at basal levels in both prostate cancer cells and the associated stromal cells." (PMID 24213506, 2012). "Down-regulation of ADAMTS15 mRNA linked to poor prognosis in prostate cancer." (PMID 24213506, 2012). "ADAMTS15 expression in prostatic cancer and associated stromal cells has been previously reported." (PMID 24213506, 2012). "In human prostate cancer, it has been observed that ADAMTS-15 was expressed in biopsies, with evidence of co-localization with VCAN and its bioactive cleavage fragment, versikine, suggesting a tumor suppressor role for ADAMTS-15 in prostate cancer." (PMID 39682243, 2024). "It was reported that ADAMTS15 played a tumor suppressor role in prostate cancer and colorectal cancer." (PMID 37234367, 2023). "ADMATS-15 plays a tumor suppressor role in prostate cancer, and the expression of ADAMTS-15 in prostate cancer is regulated by androgen." (PMID 35883515, 2022). "ADAMTS-15 was found to be expressed in human prostate cancer biopsies with evidence of co-localization with VCAN and its bioactive cleavage fragment versikine." (PMID 32354091, 2020). "Collectively, these results indicate a cell- and activity-dependent role for ADAMTS-15 in migration of late ‘castrate-resistant’ stage prostate cancer cells." (PMID 32354091, 2020). "Collectively, these data are generally consistent with ADAMTS-15 utilizing VCAN as a substrate to yield versikine in prostate cancer." (PMID 32354091, 2020). "This suggests that ADAMTS-15 represents a potential biomarker for prostate cancer, and that augmenting versican cleavage is a possible strategy for treatment." (PMID 32354091, 2020). "Together, this suggests thqat ADAMTS-15 represents a potential biomarker for prostate cancer, and that augmenting versican cleavage is a possible strategy for treatment." (PMID 32354091, 2020). "Here, we analyzed the expression of ADAMTS-15 in human prostate cancer, and investigated the effects of enforced expression in prostate cancer cell lines." (PMID 32354091, 2020). "Several of these family members also impact cancer progression, which prompted the examination of ADAMTS-15 in prostate cancer." (PMID 32354091, 2020). "Together, these data indicate that ADAMTS-15 acts as a tumor suppressor in prostate cancer, likely through cleavage of VCAN to versikine, with its in vivo effects on early-stage prostate cancer cells influenced by androgens." (PMID 32354091, 2020). "The ADAMTS-15 acted as a tumor suppressor in breast and prostate cancer." (PMID 36845403, 2023). "In this study, the role of ADAMTS-15 in prostate cancer was investigated." (PMID 32354091, 2020). "This is consistent with the hypothesis that ADAMTS-15 acts to cleave VCAN to form versikine in prostate cancer." (PMID 32354091, 2020). "Collectively, this research identifies the enzymatic function of ADAMTS-15 as having a tumor suppressor role in prostate cancer, possibly in concert with androgens, and that VCAN represents a likely key substrate, highlighting potential new options for the clinic." (PMID 32354091, 2020). "Moreover, ADAMTS-1 is also able to function as a versicanase, with evidence that it is reduced in prostate cancer, suggesting it may act in concert with ADAMTS-15." (PMID 32354091, 2020). "Of those that can cleave VCAN, ADAMTS-1 and -15 are the most highly expressed in prostate cancer cell lines, with ADAMTS-1 demonstrated to possess tumor suppressor activity in prostate cancer, and ADAMTS-15 expression shown to be androgen-dependent." (PMID 32354091, 2020).
prostate carcinoma (continued). "Enforced expression of ADAMTS-15, impacted on proliferation, survival and migration of late-stage ‘castrate-resistant’ PC-3 prostate cancer cells in vitro, which was not reproduced with a catalytically-inactive mutant." (PMID 32354091, 2020). "LNCaP represent a less malignant stage of prostate cancer than PC-3 cells, with reduced levels of both proliferation and migration as well as lower VCAN expression (data not shown), which might explain why tumor-suppressor functions for ADAMTS-15 were less readily observed in this cell line." (PMID 32354091, 2020). "Enforced expression of ADAMTS-15, but not a catalytically-inactive version, decreased cell proliferation and migration of the ‘castrate-resistant’ PC3 prostate cancer cell line in vitro, with survival increased." (PMID 32354091, 2020).
colorectal cancer (6 papers, 2012 to 2023). A primary or metastatic malignant neoplasm that affects the colon or rectum. "ADAMTS15 was found to be one of the candidate tumor suppressor genes mutated in a small set of 11 colorectal cancer samples including both cell lines and human tumor xenografts." (PMID 24213506, 2012). "However, it is noteworthy that ADAMTS15 is located at 11q24.3 in a region of frequent loss of heterozygosity in different tumors especially colorectal cancers." (PMID 24213506, 2012). "ADAMTS15 is low expressed in colorectal carcinomas and inhibits tumor growth and invasion." (PMID 34603444, 2021). "ADAMTS15 is genetically silenced in human colorectal cancer." (PMID 30081852, 2018). "ADAMTS15 also has a negative correlation with the degree of tumor tissue differentiation in colorectal cancer and inhibits the growth and invasion ability of colon cancer cells." (PMID 32884571, 2020). "Hence, ADAMTS15 functions as a tumor suppressor in colorectal cancer independent of its metalloproteinase activity." (PMID 24213506, 2012).
colon carcinoma (4 papers, 2013 to 2020). "This was consistent with a previous study showing knock-down of ADAMTS-15 in colon cancer cells resulted in increased subcutaneous tumor growth in NOD/SCID mice." (PMID 32354091, 2020). "ADAMTS9 was reduced by promoter methylation in gastric cancer cells, and ADAMTS15 was genetically inactivated in colon cancer." (PMID 28503860, 2017). "Similarly, a detailed analysis of genes downregulated in tumor samples resulted in the identification of protease genes including MMP28, ANPEP, ADAMTS1 and ADAMTS15, previously known to be repressed in colon carcinoma or in other tumor types." (PMID 24243807, 2013).
Burkitt lymphoma (1 paper, 2022). A rare form of malignant mature B-cell non-Hodgkin lymphoma. "Analysing gene expression data of Burkitt lymphoma transcriptome sequencing from African patients revealed six biomarkers (ADAMTSL4, SEMA5B, ADAMTS15, THBS2, SPON1 and THBS1) as possible indicators for diagnostic and prognostic targets towards BL management." (PMID 36354023, 2022).
glioma (1 paper, 2023). A benign or malignant brain and spinal cord tumor that arises from glial cells (astrocytes, oligodendrocytes, ependymal cells). "Tenascin-C can activate the Notch pathway to promote glioma proliferation by increasing ADAMTS15 and Jagged1 (JAG1) expression." (PMID 37325048, 2023).
intracranial aneurysm (1 paper, 2022). "In a whole exome sequencing (WES) studies, ADAMTS15 was found to be linked to intracranial aneurysm in Japanese and German families." (PMID 35234888, 2022).
melanoma (1 paper, 2020). A malignant, usually aggressive tumor composed of atypical, neoplastic melanocytes. "The cell cycle and taste transduction gene sets were enriched in high-expression groups of ARHGAP6 and ADAMTS15, respectively, whereas primary immunodeficiency and melanoma were enriched in the CHRD and SPOCK1 high-expression groups, respectively." (PMID 32218218, 2020).
metastatic tumors (1 paper, 2012). "They found that ADAM8 was expressed significantly higher in metastatic tumors as well as identifying several proteinases of the ADAM-family (ADAM9, ADAM17, ADAM28, ADAMTS1, ADAMTS8 and ADAMTS15) -including ADAM8- which are HNSCC associated." (PMID 22369429, 2012).
osteoarthritis (1 paper, 2014). A noninflammatory degenerative joint disease occurring chiefly in older persons, characterized by degeneration of the articular cartilage, hypertrophy of bone at the margins and changes in the synovial membrane. "Of note, ADAMTS15 was shown to be expressed in the joint with decreased expression in osteoarthritis." (PMID 25142923, 2014).
progeria (1 paper, 2022). "Thus, ADAMTS15 might be an interesting research target in progeria and aging-related research, especially as WNT16 is among the only three DEGs that progeria, aging, and the aging pathway have in common." (PMID 36289702, 2022). "ADAMTS15, along with ADAMTS1, 4, 5, 9, and 20, is involved in several processes, including palate formation, skin pigmentation, myogenesis, and cardiac development, all of which appear to be affected by progeria." (PMID 36289702, 2022). "Some genes that are downregulated during aging are upregulated in progeria patients (KRT8, KRT18, UCP2, ADAMTS15, ACTN4P1) while others (ACKR4) are upregulated in nonagenarians but downregulated in children suffering from HGPS." (PMID 36289702, 2022).
prostate tumors (1 paper, 2020). "Increased accumulation of ADAMTS-15 was observed in epithelial tissue of high grade prostate tumors with the highest expression detected in Gleason grade 8 samples." (PMID 32354091, 2020).